SAMD4B (sterile alpha motif domain containing 4B)
Description:
Has transcriptional repressor activity.
Synonyms: hSmaug2; SMAUG2; FLJ10211; MGC99832; SMGB
Tractability: PROTAC: ubiquitination databases record sites on it.
Gene: Protein-coding gene on chromosome 19 (39,342,421 to 39,385,710, forward strand). Ensembl gene ENSG00000179134.
Subcellular location: Cytoplasm; Nucleus
Subcellular location (Human Protein Atlas): Cytosol
Gene Ontology:
Molecular function: protein binding; RNA binding; mRNA binding; translation repressor activity
Biological process: nuclear-transcribed mRNA poly(A) tail shortening; negative regulation of translation; regulation of mRNA stability
Cellular component: cytosol; P-body; cytoplasm; nucleus
Genetic constraint (gnomAD): Loss-of-function variants: 5 observed, 73.92 expected, observed/expected ratio (o/e) 0.0676, 90% interval 0.034 to 0.14. The upper end of that interval is the gene's LOEUF score, 0.14, which puts it in group 1 of 6, group 1 being the genes least tolerant of losing a copy. Missense variants: 608 observed, 942.88 expected, observed/expected ratio (o/e) 0.64, 90% interval 0.6 to 0.69. Synonymous variants: 373 observed, 384.97 expected, observed/expected ratio (o/e) 0.97, 90% interval 0.89 to 1.06.
Homologues: Orthologues: chimpanzee SAMD4B (100% identical), macaque SAMD4B (99% identical), pig SAMD4B (98% identical), rabbit SAMD4B (97% identical), dog SAMD4B (97% identical), guinea pig SAMD4B (97% identical), mouse Samd4b (97% identical), rat Samd4b (96% identical), tropical clawed frog samd4b (72% identical), zebrafish SAMD4B (44% identical), Drosophila melanogaster smg (28% identical), Caenorhabditis elegans ZC190.4 (20% identical). Paralogues in human: SAMD4A (64% identical).